OR5M10 (olfactory receptor family 5 subfamily M member 10)
Description:
Odorant receptor.
Synonyms: OR11-207
Tractability: Antibody: UniProt places it where antibodies can reach, with medium confidence; UniProt predicts a signal peptide or a membrane-spanning region; its Gene Ontology location is reachable by antibodies, with medium confidence.
Gene: Protein-coding gene on chromosome 11 (56,576,774 to 56,577,721, reverse strand). Ensembl gene ENSG00000254834.
Subcellular location: Cell membrane
Pathways (Reactome):
Sensory Perception: Expression and translocation of olfactory receptors
Gene Ontology:
Molecular function: olfactory receptor activity; G protein-coupled receptor activity
Biological process: G protein-coupled receptor signaling pathway; sensory perception of smell; detection of chemical stimulus involved in sensory perception of smell
Cellular component: plasma membrane; membrane
Genetic constraint (gnomAD): Missense variants: 383 observed, 378.61 expected, observed/expected ratio (o/e) 1.01, 90% interval 0.93 to 1.1. Synonymous variants: 148 observed, 143.62 expected, observed/expected ratio (o/e) 1.03, 90% interval 0.9 to 1.18.
Homologues: Orthologues: chimpanzee OR5M10 (97% identical), dog OR5M10 (87% identical), rat Or5m10b (83% identical), mouse Or5m10 (82% identical), rat Or5m10 (82% identical), mouse Or5m10b (82% identical). Paralogues in human: OR5M1 (96% identical), OR5M11 (65% identical), OR5M8 (62% identical), OR5M3 (57% identical), OR5M9 (57% identical), OR8U1 (53% identical), OR9G4 (52% identical), OR8U3 (52% identical), OR5AR1 (52% identical), OR5B12 (52% identical), OR5B21 (51% identical), OR8I2 (51% identical), and 84 more.